MMP2 (matrix metallopeptidase 2)
Diseases named in the same sentence as MMP2 in open-access papers (continued):
Sharing a sentence is not in itself a finding about the gene and the disease.
melanoma (continued). "Based on this results, it is hypothesized that a powerful cell survival regulator, such as NRP1, may be a positive regulator of MMP2, and therefore promote melanoma progression, invasion and metastasis." (PMID 25954957, 2015). "LIFr knockdown reduces melanoma cell migration in part by reduced activation of MMP2." (PMID 26329521, 2015). "The MMP2/ab733 Mn3O4 NPs showed increased signal in two sites of melanoma metastasis." (PMID 24919932, 2014). "In addition, osteopontin, an ECM protein, is able to interact with αVβ3 integrin to enhance MT1-MMP expression, stimulate MMP-2 activation, and induce cell migration and invasion in murine melanoma cells." (PMID 25317077, 2014). "It is, however, noteworthy that this study was conducted using tumor tissue microarrays through the application of peroxidase developed with 3,3’-diaminobenzidine (DAB – a brown substrate), making the assessment of MMP-2 difficult to distinguish from melanoma cells in pigmented lesions." (PMID 25667918, 2014). "MMP-2 is a biomolecular and indicates prognosis in melanoma." (PMID 25203554, 2014). "In the present study, we used melanoma cells B16-F10 to investigate the inhibitory effects of wogonin on cell invasion and migration in vitro and in vivo, as well as the influences of wogonin on cytoskeleton and the expression and activity of MMP-2 and MMP-9." (PMID 25203554, 2014). "As an important adjustor, PI3-K directly affects the cooperative interactions of MT1-MMP and MMP-2 activity in highly aggressive melanoma cells, and regulates MT1-MMP activity which promotes the conversion of pro-MMP into its active conformation through an interaction with TIMP-2." (PMID 24628713, 2014). "MMP-9 is an acidic pHe-signal target gene, with the acid-induced level of MMP-9, but not MMP-2, expression positively correlated with the metastatic potential of mouse B16 melanoma variants." (PMID 25493076, 2014). "Specifically, MMP-2 is a better prognostic indicator in melanoma." (PMID 25203554, 2014). "This suggested that the inhibition of ERK l/2 signaling pathways could result in the inhibition of activities of secreted MMP-2 as well as the cell migration of melanoma cells." (PMID 25184134, 2014). "From these reviews and others we have identified five melanoma biomarkers consistently associated with melanoma progression – melanoma cell adhesion molecule (MCAM), galectin-3 (Gal-3), matrix metalloproteinase-2 (MMP-2), chondroitin sulfate proteoglycan 4 (CSPG4), and paired box 3 (PAX3)." (PMID 24069584, 2013). "Another mechanism by which CSPG4 facilitates melanoma metastasis is by its interaction with MMP-2." (PMID 24069584, 2013). "MT1-MMP traffics to these structures in cancer cells, suggesting that co-localization of αvβ3 with MT1-MMP and active MMP-2 concentrates adhesion molecules that bind matrix proteins with enzymes that degrade the matrix, thereby facilitating melanoma cell invasion." (PMID 24069584, 2013). "Previous study showed that PRAF3 could suppress the activity of MMP-2 by modulating the integrin avb3 signaling in melanoma." (PMID 22433565, 2012). "Treatment of highly metastatic murine melanoma B16F10 cells with curcumin (15 μM) for 15 days significantly inhibited matrixmetalloproteinase-2 (MMP-2) activity, which has been described to promote cell motility and metastasis formation, thus increasing the metastatic potential." (PMID 22433222, 2012). "Base on the findings of the static adhesion assay and spreading analysis, we further queried whether MMP-2 activity regulates αvβ3 integrin-mediated migration of human A375 melanoma on fibronectin." (PMID 22848537, 2012). "We investigated whether MMP-2 cleaved fibronectin to enhance the adhesion of melanoma cells mediated by αvβ3 integrin." (PMID 22848537, 2012). "Thus, we assayed MMP-2 levels in our panel of melanoma cell lines via gelatin zymography and western blot, where pro-MMP-2 appears as a 72 kDa band, and active MMP-2 appears as a ∼64 kDa band." (PMID 22745734, 2012).
melanoma (continued). "To further study the interaction between MMP-2 and αvβ3 integrin, we cultured the human A375 melanoma cells using an agarose drop model with the following steps: 2 μl drops of cells (5×106 cells/ml) in the agarose were seeded onto fibronectin-coated coverslips in a 24-well plate." (PMID 22848537, 2012). "MMP-2 (gelatinase A, 72 kDa type IV collagenase) is a matrix metalloproteinase which was first described and purified from highly metastatic murine tumors and cultured human melanoma cells." (PMID 22900195, 2012). "The most active compound, (4-{[(β-D-galactopyranosyl)oxy]methyl}furan-3-yl)methyl hydrogen sulfate (GSF), inhibited the activation of matrix-metalloproteinase-2 (MMP-2) as well as migration of the human melanoma cells of the lines WM-115 and WM-266-4 in a two-dimensional migration assay." (PMID 23015827, 2012). "To test whether the MMP-2-cleaved 120-kDa and 70-kDa bands are functional for enhancing the adhesion of melanoma mediated by αvβ3 integrin, we retrieved the fragments from the native gel and coated them on 24-well flat-bottom plates." (PMID 22848537, 2012). "The most extensively studied MMPs in melanomas are MMP-2 and MMP-9." (PMID 20631829, 2010). "In this regard, this activated form could be detected by zymography in supernatants of all melanoma cell lines that cross-presented the MMP-2 epitope 560–568 (Godefroy personal communication)." (PMID 20689590, 2010). "We recently described the recognition, on about half HLA-A2 melanoma cell lines, of a new HLA-A2-restricted tumor antigen derived from Matrix Metalloproteinase 2 (MMP-2) by a CTL clone (M134.12) derived from Tumor Infiltrating Lymphocytes (TILs) of a melanoma patient." (PMID 20689590, 2010). "Because of its role in melanoma progression, targeting the MMP-2 antigen by immunotherapy might be particularly effective by limiting the potential selection of antigen loss variants." (PMID 20689590, 2010). "The secretion of MMP-2 from another tumor cell line, B16-F10 melanoma cells, was also studied." (PMID 18597698, 2008). "No other significant associations were found between the MMP2 SNPs and the phenotypic and clinico-pathological melanoma features." (PMID 17958893, 2007). "FAPα associates with DPPIV, MMP-2, membrane-type 1 MMP and urokinase plasminogen activator receptor at invadopodia of human malignant melanoma cells and so may interact with these proteinases and receptors and associated cascades." (PMID 16507127, 2006). "Our study demonstrates that of all tested components of the matrix metalloproteinase system, only expression of activated MMP-2 correlates with increased malignancy in our melanoma xenograft model, corroborating an important role of MMP-2 in human melanoma invasion and metastasis." (PMID 10555745, 1999). "Moreover, brain-metastasizing melanoma cells have the capacity to reprogram astrocytes, leading to the expression of the pro-inflammatory cytokine IL-23, which in turn increases MMP-2 levels and facilitates melanoma cell migration and invasion into the brain parenchyma." (PMID 39780275, 2025). "Ultimately, as indicated by the modest decrease in MMP2 expression levels in the BRAF-mutated cell lines, this finding may contribute to elucidating the previously reported reduction in cell mobility and colony formation within the same melanoma cell lines." (PMID 38338893, 2024). "Among these, whether MMP2 functions as an immunosuppressive role in melanoma, remains unclear." (PMID 36788565, 2023). "Altogether, our findings suggest that gastrin may exert both direct and indirect effects on melanoma cells by enhancing their migration and invasion capabilities, possibly by altering the balance towards the dominance of secreted proteases, e.g., MMP-2, against protease inhibitors, e.g., TIMP-3." (PMID 38069171, 2023).
melanoma (continued). "With the evidence that MMP2 expression increased CAFs infiltration, we further investigated whether MMP2 inhibitor has synergistic efficacy with anti-PD-1 therapy in a mouse model of melanoma." (PMID 36788565, 2023). "Furthermore, vemurafenib resistance in melanoma cells was attributed to the activity of MMP-2." (PMID 35586209, 2022). "Studies indicate that melanoma cells with an increased expression of Wnt5a induce an instantaneous extrication of exosomes that contain immunomodulatory cytokines IL-6 and pro-angiogenic factors IL-8, matrix metallopeptidase 2 (MMP2), and vascular endothelial growth factor (VEGF) in their cargo." (PMID 34575889, 2021). "Moreover, the role of MMP-2 in human melanoma invasion and metastasis is also important." (PMID 34207884, 2021). "Finally, TIMP-2 was shown to contribute to the activation of MMP-2 at the cell membrane in vitro and in vivo, and may thereby promote melanoma cell invasiveness." (PMID 33846376, 2021). "MMP2 was found to be expressed in samples of human melanoma-associated spongiform scleropathy, whereas MMP13 could not be detected in this study." (PMID 33966129, 2021). "In addition to regulating the transcription of cell cycle and apoptosis related target genes, Stat3 activation in melanoma cells controls matrix metalloproteinase-2 (MMP-2) expression through interacting with MMP-2 promoter, thus promoting melanoma invasion and metastasis." (PMID 32565740, 2020). "Moreover, since B16.F1 melanoma cells show low metastatic capability, whether the final outcome of these opposite effects in migration and MMP-2 and MMP-9 activities would be pro- or anti-metastatic needs to be addressed." (PMID 33202705, 2020). "Moreover, the intratumor production of the transcription factor AP-1 (c-Jun subunit) that regulates the expression of MMP-2 as well as the levels of HIF-1 (α subunit, HIF-1α), that are tightly linked to the aggressive phenotype of melanoma cells, were determined via Western blot." (PMID 32340166, 2020). "Indeed, a previous study showed that acidic pH promotes experimental pulmonary metastasis of human melanoma cells in athymic nude mice by up-regulating the expression of the proteolytic enzymes MMP-2, MMP-9, cathepsin B, and cathepsin L and the proangiogenic factors VEGF-A and IL-8." (PMID 30836626, 2019). "Moreover, we did not notice changes in MMP‐2 activity in analysed variants of melanoma cell lines (data not shown)." (PMID 31638339, 2019). "Thus, we analyzed MMP2 activation in melanoma clones under normoxia and hypoxia." (PMID 29238043, 2017). "Therefore, CoQ0 may inhibit melanoma metastasis through the suppression of MMP-2, and MMP-9 expression." (PMID 26968952, 2016). "In addition, the incidence and counts of lung metastases were significantly lower in ACTIBIND-treated mice, which corroborated with the reduced matrix metalloprotein 2 (MMP2) expression and activity recorded in both melanoma and human umbilical vascular endothelial cells (HUVEC)." (PMID 27014725, 2016). "Furthermore, STAT3 regulates the expression of mmp2 in melanoma cells." (PMID 25671570, 2015). "In addition, MMP2 is involved in the autocrine regulation of VEGF A expression in melanoma cells." (PMID 25954957, 2015). "The human melanoma cell lines A-07, D-12, R-18, and U-25 showed characteristic patterns of vascularization and invasion in the brain, and these differences were associated with differences in expression of the angiogenic factors VEGF-A and IL-8 and the matrix metalloproteinases MMP-2 and MMP-9." (PMID 26667022, 2015). "We report that the melanoma cell lines showed highly different patterns of vascularization and invasion in the brain and, furthermore, these differences were associated with differences in expression of the angiogenic factors VEGF-A and IL-8 and the matrix metalloproteinases MMP-2 and MMP-9." (PMID 26667022, 2015).
melanoma (continued). "Human melanoma cells were seeded using an agarose drop model and/or subjected to in vitro analysis using immunofluorescence, adhesion, migration and invasion assays to investigate the relationship between active MMP-2 and αvβ3 integrin during the adhesion and migration of the tumor cells." (PMID 22848537, 2012). "Therefore, we investigated whether MMP-2 activity affects the spreading of human A375 melanoma cells." (PMID 22848537, 2012). "Since it was reported that PRAF3 inhibited melanoma metastasis by integrin aVb3 signaling and integrin aVb3 could promote tumor metastasis by activating MMP-2, we further analyzed the expression of integrin aV and b3 subunits in ESCC cells infected with Ad.PRAF3 (or Ad.Null) by western blot." (PMID 22433565, 2012). "Thus, a specific role for BRG1 in the activation of MMP2 and melanoma invasiveness may result from selective interactions with the SP1 transcriptional regulator." (PMID 20969766, 2010). "MMI‐166, a third‐generation inhibitor targeting MMP‐2 and MMP‐9, demonstrated reduced tumour proliferation in mice injected with B16‐BL6 melanoma cells." (PMID 41546170, 2026). "Together, AA and NG effectively suppressed invasion and metastasis of melanoma and lung carcinoma by modulating TGF‐β/Smad‐dependent MMP2 transcription, post‐translational activation and function." (PMID 41546170, 2026). "A study by Lian found that AA combined with naringenin inhibited both metastasis and invasion of melanoma and lung cancer cells via the TGF-β-Smad-MMP2 pathway." (PMID 41011581, 2025). "As well as curcumin, imatinib, and thalidomide have all been shown to inhibit melanoma VM, concomitant with decreases in EPHA2, VE-cadherin, PI3K, VEGF, HIF-1, MMP-2, and MMP-9 expression and/or activity." (PMID 40507830, 2025). "In transdifferentiated A375 cells the melanoma markers MKI67, MITF, S100A4, S100A10, MMP2 and MMP9 were significantly downregulated." (PMID 40715046, 2025). "In human melanoma (A375) cells, apigenin down-regulates STAT3 target genes matrix metalloproteinase 2 (MMP-2) and MMP-9, thereby suppressing tumor growth and invasion." (PMID 40490812, 2025). "The melanoma cell line MEWO, characterized by aggressive behavior and high MMP-2 activity, was used as a model to evaluate the effect of mTOR pathway inhibitors on cell invasion." (PMID 40869090, 2025). "The activities of two metalloproteinases, MMP-2 and MMP-9, were studied in the primary WM3211 and metastatic Mel-1359 and MEWO melanoma cell lines after 24 h and 48 h treatment with mTOR inhibitors and their combinations." (PMID 40869090, 2025). "In vitro experiments have exhibited that wogonin inhibited NF‐kB, PI3K/Akt, MMP‐2, PI3K/Akt, Rac‐1, and ERK signaling pathways to reduce adhesion, actin remodeling in B16‐F10 melanoma cells, invasion, and cellular migration." (PMID 41164269, 2025). "In melanoma, CXCL8 is a multifunctional cytokine that promotes neo-vascularization, activates MMP-2, and enhances anoikis resistance." (PMID 40717170, 2025). "Prominent MMPs, including MMP-1, MMP-2, MMP-3, MMP-9, MMP-13, and MMP-14, have been shown to significantly contribute to the development of melanoma." (PMID 39769318, 2024). "Several studies have shown that melanoma cells can express a specific pool of MMPs (MMP-1, MMP-2, MMP-9, MMP-13, and MT1-MMP) as well as their tissue inhibitors (TIMP-1, TIMP-2, and TIMP-3)." (PMID 39594665, 2024). "Apigenin stopped melanoma cell motility and invasion by downregulating STAT3 target genes (TWIST1, MMP-2, MMP-9, and VEGF)." (PMID 38398617, 2024). "Mulberry anthocyanins, cyanidin 3-rutinoside and cyanidin 3-glucoside, are capable of inhibiting the expression of MMPs, in particular MMP-2, and plasminogen activator-urokinase (PAI) in metastatic lung cancer and melanoma cells (A549, B16-F1)." (PMID 38540096, 2024).
melanoma (continued). "Another phenolic acid, bornylcis-4-hydroxycinnamate, was demonstrated to be able to decrease the expression of MMP-2 and MMP-9 by inhibiting FAK/PI3K/Akt/mTOR, MAPK and GRB2 signaling pathways in melanoma cells." (PMID 38540096, 2024). "Luteolin downregulates MMP-2 and MMP-9 expression via the PI3K/AKT pathway to decrease melanoma cell growth and induce apoptosis." (PMID 38398617, 2024). "Roomi and colleagues assessed the role of EGCG in the regulation of MMP-2 and MMP-9 in human melanoma A-2058 cells using a gelatinase zymography assay and densitometry analysis." (PMID 39335164, 2024). "Next, as metalloprotease activity is related to melanoma invasion, we observed MMP-9 and MMP-2 in SK-MEL-28 by zymogram assay." (PMID 38399442, 2024). "For example, a study analyzing the expression of MMPs in melanoma found that MMP-1, MMP-2, MMP-3, MMP-7, MMP-9, and MMP-13 showed increased levels in melanoma tissues compared to normal tissues." (PMID 39200315, 2024). "MMP-2/9 gelatinase activity was also found in murine syngeneic tumors grown in immune-competent mice established from lung (LL2), colorectal (MC38), and melanoma (B16) murine cancer cell lines." (PMID 39683778, 2024). "After quercetin therapy, melanoma cells downregulate STAT3-targeted genes MCL-1, MMP-2, MMP-9, and VEGF, which increase cell proliferation, migration, and invasion." (PMID 38398617, 2024). "Further research on the anti-proliferative properties of Bai in melanoma cell lines (A375 and SK-MEL-28) revealed a significant reduction in MMP-2 expression in Bai-treated cells." (PMID 38672151, 2024). "It increases the proliferation, migration, and invasion of melanoma cells as well as VM tube formation through ST2, possibly via the induction of MMP‐2/9 production through ERK1/2 phosphorylation." (PMID 38775220, 2024). "The GH-treated melanoma cells released exosomes with elevated levels of ABC transporters (ABCC1 and ABCB1), N-cadherin, and MMP2, enhancing drug resistance and migration in the recipient cells." (PMID 39123364, 2024). "Genistein also induced a concentration-dependent reduction in the secretion and expression of MMP-2 and MMP-9 in melanoma 518 A2 cells, with a stronger effect than two other flavones: chrysin and apigenin." (PMID 39335164, 2024). "MMP-2 and MMP-9 are overexpressed in melanoma cells and positively correlated with highly metastatic tumor behavior, while their endogenous inhibitors, TIMP-1 and -2, are down-regulated in melanoma cells, exhibiting aggressive potential." (PMID 38247872, 2024). "Several studies have shown that the expression and activity of MMP-2 and MMP-9 are increased in melanoma cells compared to normal skin cells." (PMID 37504268, 2023). "MMP-2 and MMP-9 are secreted by both melanoma cells and stromal cells in the tumor microenvironment." (PMID 37504268, 2023). "MMP-2 (matrix metalloproteinase-2) and MMP-9 (matrix metalloproteinase-9) have also been studied in the context of melanoma progression and metastasis." (PMID 37504268, 2023). "Among the members of the MMP family, MMP‐2 and MMP‐9 have been reported to correlate with the invasive phenotype of melanoma." (PMID 37038620, 2023). "Previous studies reported that compared with NMM, the expression levels of SNAI2, MMP2, MIF, and AP1S2 were up-regulated in MM and were crucial roles in the metastasis and malignant progression of melanoma." (PMID 37880239, 2023). "For melanoma tumors established from B16F10 cells, AuNPs increased vascular perfusion and decreased permeability, together with reducing MMP-2 expression levels, which decreased the probability of metastasis." (PMID 37373007, 2023). "In melanoma, METTL3 activity augments the expressionof matrixmetallopeptidase 2 (MMP2), thereby increasing the motility of humanmelanoma cells and facilitating migration and invasion." (PMID 36692498, 2023).